IMPDH1 (inosine monophosphate dehydrogenase 1)
Diseases named in the same sentence as IMPDH1 in open-access papers (continued):
Sharing a sentence is not in itself a finding about the gene and the disease.
retinal diseases (3 papers, 2021 to 2023). "Mutations in IMPDH1 have been linked to various retinal diseases, including the autosomal dominant retinitis pigmentosa (adRP), a genetic eye disorder that affects approximately 1 in 4000 people." (PMID 37731818, 2023). "The occurrence of de-novo mutations is rare in retinal disease genes and a heterozygous de-novo mutation in IMPDH1 was detected in one affected individual in our cohort." (PMID 34662339, 2021). "Understanding these relationships provides valuable insights into the molecular dynamics of photoreceptor cells and may contribute to the development of targeted therapeutic approaches for retinal diseases associated with dysregulated IMPDH1 activity." (PMID 37731818, 2023).
acute myeloid leukaemia (2 papers, 2025). "In hematological cancers like mantle cell lymphoma (MCL), diffuse large B-cell lymphoma (DLBCL), chronic lymphocytic leukemia (CLL), acute myeloid leukemia (AML), and anaplastic large cell lymphoma (ALCL), IMPDH2 levels are significantly higher than IMPDH1." (PMID 41154443, 2025).
autoimmune disease (2 papers, 2020 to 2024). A disorder resulting from loss of function or tissue destruction of an organ or multiple organs, arising from humoral or cellular immune responses of the individual to their own tissue constituents. "Inhibitors of IMPDH1 e.g. MPA and others are currently applied clinically in the treatment of autoimmune diseases and prevention of organ transplant rejection." (PMID 33520699, 2020).
colorectal cancer (2 papers, 2020 to 2023). A primary or metastatic malignant neoplasm that affects the colon or rectum. "Real‐time quantitative PCR and immunoblotting were, respectively, used to examine the mRNA and protein of inosine monophosphate dehydrogenase 1 (IMPDH1) in human colorectal cancer (CRC), azoxymethane/dextran sulphate sodium‐induced mouse CRC and spontaneous intestinal tumours from APCMin/+ mice." (PMID 36629054, 2023).
leukemia (2 papers, 2023 to 2025). A malignant (clonal) hematologic disorder, involving hematopoietic stem cells and characterized by the presence of primitive or atypical myeloid or lymphoid cells in the bone marrow and the blood. "We then assessed the role of IMPDH1 and IMPDH2 in MLL‐fusion leukemias using the CRISPR/Cas9 system." (PMID 36453131, 2023). "Likewise, leukemia and multiple myeloma cell lines mainly express IMPDH2 with little IMPDH1." (PMID 41154443, 2025).
ovarian carcinoma (2 papers, 2019 to 2022). A malignant neoplasm originating from the surface ovarian epithelium. "IMPDH1 expression was negatively correlated with survival in those cancer patients except for ovarian cancer." (PMID 36618420, 2022).
small cell lung carcinoma (2 papers, 2020 to 2025). Small cell lung cancer (SCLC) is a highly aggressive malignant neoplasm, accounting for 10-15% of lung cancer cases, characterized byrapid growth, and early metastasis. "IMPDH1 is constitutively expressed in normal lymphocytes but is highly upregulated in a subset of small cell lung cancers (SCLC)." (PMID 41154443, 2025).
B-cell lymphomas (1 paper, 2025). "IMPDH1 and IMPDH2 are highly expressed in proliferative lymphoid malignancies, including T- and B-cell lymphomas." (PMID 41154443, 2025).
bladder urothelial carcinoma (1 paper, 2023). "In human bladder urothelial carcinoma (BLCA) tissues, the proteins expression of IMPDH1, IMPDH2, and TWIST1 was up-regulated." (PMID 37215997, 2023).
Down syndrome (1 paper, 2023). "This case report of a 13-year-old girl with Down's syndrome and keratoglobus is aimed at linking the novel variant IMPDH1 c.134A>G, p.(Tyr45Cys), a variant of uncertain significance, to a clinical phenotype and to provide grounds for the objective assignment of its benign features." (PMID 37569264, 2023).
esophageal cancer (1 paper, 2024). A primary or metastatic malignant neoplasm involving the esophagus. "From a clinical perspective, our results indicate the aberrantly high expression of IMPDH1 in esophageal cancer tissues and its close association with patient prognosis." (PMID 38702629, 2024). "Further analysis within the esophageal carcinoma subtype indicated notably higher IMPDH1 expression in squamous cell carcinoma compared to adenocarcinoma (p < 0.01)." (PMID 38702629, 2024). "Specifically in primary esophageal carcinoma tissues, IMPDH1 mRNA levels were significantly higher than those in adjacent normal tissues, underscoring its potential significance in esophageal carcinoma." (PMID 38702629, 2024).
hepatitis B virus (1 paper, 2019). "Six IA genes, APOB, IMPDH1, SEC61G, IQGAP2, TAGAP, and IGKV4-1, were dysregulated (differential expression, p < 0.05) in only tumor samples of drinkers without hepatitis B virus (HBV) infection as compared to pure normal samples (from nondrinkers)." (PMID 31480259, 2019).
intestinal tumours (1 paper, 2023). "Interestingly, high IMPDH1 protein expression was also observed in spontaneous intestinal tumours from APCMin+ mice." (PMID 36629054, 2023).
retinal dystrophies (1 paper, 2020). "We propose that IMPDH1 mutations lead to retinal dystrophies by disrupting this mechanism of control." (PMID 32254022, 2020). "This study gains insight into the complex in vivo regulation of IMPDH1 to maintain GTP homeostasis with changing illumination, central to rod dark/light physiology and relevant to understand IMPDH1-inherited retinal dystrophies." (PMID 32254022, 2020).
tumor (27 papers, 2008 to 2026). "IMPDH1, a key enzyme in the nucleotide synthesis pathway, has been associated with cell proliferation and tumor development." (PMID 38702629, 2024). "At first time, we examined the correlation of IMPDH1 with tumor associated immune cells by using three different sources data, reflecting that IMPDH1 had a strong relationship with a large proportion of immune cells in most tumors." (PMID 36618420, 2022). "Consistent with our estimated results, high expression of IMPDH1 was closely associated with low therapeutic response and poor prognosis in tumor patients receiving immunotherapy." (PMID 36618420, 2022). "Firstly, we analyzed the association between IMPDH1 and a gene-set capable of activating tumor immunity in pan-cancer, and a gene-set capable of suppressing tumor immunity from TCGA database." (PMID 36618420, 2022). "Furthermore, the upregulation of IMPDH1 has been linked to uncontrolled cell proliferation, suggesting its potential importance in tumor initiation and progression." (PMID 38702629, 2024). "Thus, loss of IMPDH1 leads to suppress tumor growth and progression, and these results demonstrate that IMPDH1 molecules appear to sustain tumor growth and aggressiveness." (PMID 35403278, 2022). "Mechanistically, IMPDH1 cytoophidia stabilize and translocate Y-box binding protein 1 into the nucleus to promote tumor metastasis." (PMID 39337544, 2024). "Lastly, the complexity of the tumor microenvironment and its potential influence on FGL1 and IMPDH1 regulation necessitate additional investigation to fully comprehend the interplay between these molecules and the tumor immune response." (PMID 38702629, 2024). "Changes in IMPDH1 and IMPDH2 expression cause abnormal guanine biosynthesis, affecting tumor cells physiologically." (PMID 37215997, 2023). "In nude mice, the IMPDH1 inhibitory drug MMF inhibited tumor growth and reduced the expression of tumor stem cell characteristic markers CD133 and SOX2." (PMID 36711025, 2023). "In this subgroup, induction of IMPDH1 expression and dependence was necessary and sufficient, and IMPDH1 inhibitors were able to inhibit tumor growth in xenograft and in situ genetically engineered mouse models." (PMID 36711025, 2023). "In vivo, MMF was shown to inhibit IMPDH1 expression, inhibit tumor growth, and promote apoptosis of HCCC-9810 cells." (PMID 36711025, 2023). "At least two of the top 4 m-6-A modified protein-encoding genes were positively correlated with tumor-associated macrophages and neutrophils in HCC, displaying it is possible that IMPDH1 remodeled TIME through m-6-A modified proteins." (PMID 36618420, 2022). "In vivo analysis using xenograft tumors also revealed MYBL2 regulated purine synthesis by regulating IMPDH1, and thus, influencing tumor progression." (PMID 36494680, 2022). "We found that the cytoplasmic expression of IMPDH1 protein in tumors was significantly higher than in adjacent tumor‐free liver tissues (n = 154, p < 0.001)." (PMID 35403278, 2022). "We observed that the expression of IMPDH1 is upregulated in tumor tissue compared with adjacent liver tissue in 154 HCC patients, and higher expression of IMPDH1 is associated with better patient cumulative survival in our study." (PMID 35403278, 2022). "It has been preliminarily confirmed that IMPDH1 had a great influence on the infiltration of immune cells in the tumor immune microenvironment, and the immunotherapy effect was closely related to the immune checkpoint expressed on the surface of immune cells." (PMID 36618420, 2022). "The immunohistochemistry results suggested that the expression of TM4SF1, FASN, and IMPDH1 was significantly elevated in tumor tissue specimens, while the expression of KCNK5 and KCNJ15 was downregulated." (PMID 35480865, 2022). "At first time, we conducted expression analysis of IMPDH1 in 33/31 types of tumor-normal corresponding tissue from TCGA and GTEx database." (PMID 36618420, 2022).
tumor (continued). "Relatively high expression in advanced tumors (Stages 3/4), indicating that IMPDH1 was involved in the tumor progression, the advanced stage of the tumors, especially." (PMID 36618420, 2022). "In summary, IMPDH1 is highly expressed in tumor tissues and influences the modification of immune microenvironment." (PMID 36618420, 2022). "The expression of IMPDH1 is upregulated in tumor tissue compared with adjacent liver tissue, and higher expression of IMPDH1 is associated with better patient cumulative survival." (PMID 35403278, 2022). "In experimental models, loss of IMPDH1 in HCC cells inhibits the ability of single cell colony formation in vitro, and reduces the efficiency of tumor initiation and growth in immunodeficient mice." (PMID 35403278, 2022). "At present, immunotherapy gradually highlights its advantages in tumor treatment, promoting us to conduct analysis of the relationship between IMPDH1 with immune factors, such as immune cells and immune-related genes." (PMID 36618420, 2022). "IMPDH1 affects a variety of immune cells in tumor immune microenvironment and is closely related to multiple immune-related pathways." (PMID 36618420, 2022). "To further explore the impact of IMPDH1 on tumor development, we first discussed the role of IMPDH1 in tumor immune microenvironment (TIME)." (PMID 36618420, 2022). "Meanwhile, IMPDH1 expression influenced the efficacy and prognosis of tumor patients treated with immune checkpoint inhibitors." (PMID 36618420, 2022). "The Hub gene was identified and constructed based on 6 genes (KLRB1, KLF2, S100A9,MSC,ANXA5 and IMPDH1), which will help to for a predictive analysis of the tumor immune microenvironment in HCC patients." (PMID 35992798, 2022). "Of course, in some types of tumors such as HNSC, CESC, ESCA, IMPDH1 was negatively related to both immune activating, and immunosuppressive genes, which represented the complexity of IMPDH1 in tumor immune regulation." (PMID 36618420, 2022). "IMPDH1 not only had the potential as a tumor prognostic marker and therapeutic target, but also was closely related to immune cells, immune checkpoints and immune-related genes and pathways in the tumor immune microenvironment (TIME)." (PMID 36618420, 2022). "Loss of IMPDH1 in HCC cells inhibits the ability of single cell colony formation in vitro, and reduces the efficiency of tumor initiation and growth in immunodeficient mice." (PMID 35403278, 2022). "Tumors with high levels of IMPDH1 showed a faster tumor formation and growth compared with tumors with low levels of IMPDH1." (PMID 36494680, 2022). "We found that the expression of IMPDH1 is significantly higher in tumor of HCC patients when compared to adjacent liver tissue." (PMID 35403278, 2022). "Utilizing single-cell sequencing analysis and experiments in vivo and in vitro to find and verify the specific cell subtypes and molecular mechanisms of IMPDH1’s immunoregulation in the tumor microenvironment." (PMID 36618420, 2022). "Functionally, loss of IMPDH1 in HCC cells impaired colony formation in vitro and tumor initiation/growth in mice,suggesting that higher expression of IMPDH1 sustained tumor growth and aggressiveness." (PMID 35403278, 2022). "It was recently reported that IMPDH1 cooperated with metastasis-related protein Y-box binding protein 1 (YB-1) and thus promoted tumor metastasis." (PMID 33520699, 2020). "Our findings emphasize that inhibition of IMPDH could repress the proliferation, migration and invasion capabilities of HNSCC cells by decreasing GTP production, expanding the scope of IMPDH1 inhibitors in anti-tumor therapy." (PMID 38886346, 2024). "Additionally, our findings elucidate the dysregulation of IMPDH1-regulated purine biosynthesis in high-risk patients, presenting an opportunity for targeted therapy using IMPDH inhibitors to inhibit tumor progression." (PMID 38886346, 2024). "In summary, inhibition of the purine metabolism gene IMPDH1 inhibited the growth of tumor in mice." (PMID 36711025, 2023).
tumor (continued). "IMPDH1 was found to be significantly upregulated in tumor tissue and it was demonstrated that IMPDH1 could be a novel therapeutic target in vitro." (PMID 36816023, 2023). "This study intends to explore the specific role of IMPDH1 in tumors to determine whether it is suitable as a key tumor biomarker, whether it can regulate tumor immunity, and whether it has an important impact on the immunotherapy of tumor patients." (PMID 36618420, 2022). "Thus, we analyzed the correlation between IMPDH1 and Immune score, Stromal score, Tumor purity score at the same time." (PMID 36618420, 2022). "Finally, we focused on the function of IMPDH1 in BC and found that cell proliferation and colony formation were significantly inhibited after knocking down IMPDH1, implying that IMPDH1 has a tumor-promoting effect." (PMID 35480865, 2022). "Furthermore, using a combination of metabolomics and genomic analysis, we demonstrate that MYBL2 promotes de novo purine anabolism by up-regulating IMPDH1 at transcriptional level, facilitating tumor growth in vivo." (PMID 36494680, 2022). "In addition, the design of specific IMPDH1 inhibitors and related clinical trials will certainly contribute to the development of tumor immunotherapy." (PMID 36618420, 2022). "In addition, the OS, DSS and PFS of some tumor patients were also closely related to IMPDH1 methylation level." (PMID 36618420, 2022). "However, due to the different types of tumors, the effect of IMPDH1 on tumor microenvironment scores also yielded opposite results, and how IMPDH1 affected tumor progression was still unclear, further work was needed to explore the content of this part." (PMID 36618420, 2022). "In conclusion, the expression of IMPDH1 is upregulated in the tumor tissues." (PMID 35403278, 2022). "In addition, we evaluated IMPDH1 expression in tumors and their paired adjacent tissues, which showed that in 14 kinds of tumors IMPDH1 were expressed higher in tumor tissue than paired adjacent tissue, and just KICH had the opposite result." (PMID 36618420, 2022). "Furthermore, we evaluated DFS, PFS, and DSS with TCGA database, and results suggested that tumor patients with high IMPDH1 expression usually had worse prognosis in LIHC, BLCA, CESC, KIRC KIRP, LGG, MESO, UVM." (PMID 36618420, 2022). "The correlation between IMPDH1 and Immune score, Stromal score, Tumor purity in the tumor microenvironment suggested that more than one-third of types of cancers in pan-cancer are positively related to Estimate Score, and about one-third are negatively correlated with Estimate Score." (PMID 36618420, 2022). "In two-thirds of pan-cancer tumors, the association of IMPDH1 with Tumor purity score and Estimate score was statistically significant, which meant that IMPDH1 could influence tumor development by modifying tumor microenvironment in most tumors." (PMID 36618420, 2022). "In a mouse model of non-small cell lung cancer (NSCLC), inhibition of IMPDH1 expression reduced the expression of RNA polymerase-I-dependent pre-ribosomal RNA expression, inhibited the growth of tumor cells, and improved the survival of NSCLC model mice treated with chemotherapy." (PMID 33221754, 2020). "As miR-19a was expressed at a significantly highly level in MCF-7 cells, it is considered that the IMPDH1 and NPEPL1 proteins might function as tumor suppressors if they are associated with tumorigenesis under the control of miR-19a." (PMID 22952885, 2012). "As a potential therapeutic target, IMPDH1 may play a critical role in tumor immunotherapy." (PMID 36618420, 2022). "In addition, IMPDH1 was positively related to immune-related genes, no matter whether the genes were associated with activation or suppression of immunity, which suggested a complex state of IMPDH1 against tumor immunity." (PMID 36618420, 2022). "Xenograft experiment was performed on mice, followed by drug administration, measurement of tumor growth and determination of CES2, IMPDH1 and IMPDH2 expressions." (PMID 38419324, 2024).